CD22 (CD22 molecule)
Diseases named in the same sentence as CD22 in open-access papers (continued):
Sharing a sentence is not in itself a finding about the gene and the disease.
non-small cell lung carcinoma (2 papers, 2022 to 2024). A group of at least three distinct histological types of lung cancer, including non-small cell squamous cell carcinoma, adenocarcinoma, and large cell carcinoma. "Recently, it was suggested that ADAM28 might play a role in key immunomodulatory mechanisms since CD20+/CD22+/ADAM28+ B cells were shown to promote response to immune checkpoint inhibitor therapy in non-small-cell lung cancer." (PMID 36685493, 2022).
sinusoidal obstruction syndrome (2 papers, 2017 to 2026). "CD33- and CD22-targeted ADCs conjugated to calicheamicin, such as GO and InO, are consistently associated with hepatotoxicity and sinusoidal obstruction syndrome." (PMID 41596669, 2026).
tonsil carcinoma (2 papers, 2023). A carcinoma that involves the tonsil. "CD22 is broadly known as a marker of B cells, so we used tonsil carcinoma which is rich of B cells as positive controls." (PMID 37817249, 2023). "Tissue sample of tonsillar carcinoma was used as positive control of CD22 expression in IHC staining." (PMID 36768478, 2023). "Staining showed CD22 was strongly expressed in lymphnodules of tonsil carcinoma." (PMID 37817249, 2023).
type 1 diabetes (2 papers, 2021 to 2026). "For instance, CD22 and CD72 inhibited the proliferation of regulatory B cells, which can regulate MS and type 1 diabetes mellitus (T1D)." (PMID 34539413, 2021).
amyloid (1 paper, 2021). "Here, we report that CD22 is upregulated by microglia during aging and in plaque-associated microglia in the amyloid mouse model PS2APP." (PMID 34140954, 2021). "Since also distinct transcriptional microglia states e.g. DAMs (disease-associated microglia) have been identified in amyloid mouse models of age-related neurodegenerative disorders, we wondered whether CD22 is differentially expressed in these subpopulations." (PMID 34140954, 2021). "To evaluate the relevance of CD22 in an AD-related context, we used the transgenic amyloid mouse model PS2APP." (PMID 34140954, 2021). "In addition to aging, we also observed a specific upregulation of CD22 in Aβ-containing microglia in the amyloid mouse model PS2APP CX3CR1-GFP." (PMID 34140954, 2021). "Furthermore, in the amyloid mouse model PS2APP, Aβ-containing microglia also exhibit increased CD22 signal." (PMID 34140954, 2021).
aplastic anemia (1 paper, 2024). Anemia resulting from bone marrow failure (aplastic or hypoplastic bone marrow). "While the literature lacks extensive documentation on the relationship between HLA-B*49:01:01 and CLL, as noted in the context of its association with CD22, this particular allele appears to serve as a promising marker for aplastic anemia." (PMID 39329950, 2024).
atherosclerosis (1 paper, 2023). A disease characterized by the build-up of fatty material and calcium deposition in the arterial wall resulting in partial or complete occlusion of the arterial lumen. "While many immune pathways were enriched in the upregulated DEGs (e.g., CXCR5, IL21R, CCR7 and CD22) (A,C), pathways such as “lipid and atherosclerosis’ and “fluid shear stress and atherosclerosis” were enriched in the downregulated DEGs (such as NOS3, KLF2 and KLF4)." (PMID 37218991, 2023).
autistic disorder (1 paper, 2014). "Patient CD5 had language delay (LD) and DD during his childhood, and his two sons (CD21 and CD22) displayed absence of speech, DD and autistic disorder." (PMID 24603971, 2014).
bacteremia (1 paper, 2020). "CBA/Ca mice and gene-targeted CD22-deficient mice on a C57BL/6 background are both similarly susceptible to pneumococcal infection, as shown by bacterial replication in the lungs, high bacteremia and early death." (PMID 32324805, 2020).
chronic leukemia (1 paper, 2025). A slowly progressing leukemia characterized by a clonal (malignant) proliferation of maturing and mature myeloid cells or mature lymphocytes. "Flow cytometry (chronic leukemia immunophenotyping) revealed CD5 positivity, CD23 positivity, Sm Ig weak positivity, CD22 or CD79b weak, CD10 negativity, and FMC7 negativity." (PMID 40815495, 2025).
chronic myeloid leukemia (1 paper, 2023). "In another phase I trial, CD22 CAR T-cell therapy was evaluated in 58 patients with relapsed/refractory CD22+ malignancies (56 with B-ALL, one DLBCL and one chronic myeloid leukemia with ALL blast crisis)." (PMID 37296844, 2023).
co-infection (1 paper, 2024). "Lastly, the upregulation of B-cell markers (MHC II, B-cell receptor CD22, Ig-domain containing protein) was also seen in the gills, mainly in the Tb single and/or co-infection groups." (PMID 38803570, 2024).
cutaneous melanoma (1 paper, 2016). A primary melanoma arising from atypical melanocytes in the skin. "Thus, B cells may be recruited to normal skin and cutaneous melanoma sites, based on expression of the humoral immune cell markers CD20, CD22 and AID." (PMID 27411958, 2016).
demyelination (1 paper, 2026). "Bhlhe41- or Aurka-deficient young mice exhibited aging-like microglial morphology, phagocytic deficits, progressive CD22 upregulation, and remyelination impairment in cuprizone-induced demyelination model." (PMID 41896238, 2026).
diabetes (1 paper, 2014). "Another recent paper also showed that anti-CD22 immunotherapy can deplete and reprogram B-cells, therapy reversing autoimmne diabetes in naïve NOD mice." (PMID 24663217, 2014).
E. coli infections (1 paper, 2020). "We conclude that both after S. pneumoniae and E. coli infections CD22-/- mice have an impaired IRA B cell population in the lung, with impaired GM-CSF and IgM production, and therefore lack an important mechanism for protection against bacterial infections." (PMID 32324805, 2020).
emphysema (1 paper, 2019). "In humans, CD22 has been observed to positively associate with regional emphysema severity of the lungs and is regarded as a potential causal gene for airflow obstruction." (PMID 30828372, 2019).
eosinophilia (1 paper, 2013). "A recent study demonstrated that intestinal eosinophils express high levels of the pan B cell marker, CD22, which negatively regulates tissue eosinophilia." (PMID 24116141, 2013).
esophageal squamous cell carcinoma (1 paper, 2023). Esophageal squamous cell carcinoma (ESCC) is a type of esophageal carcinoma (EC) that can affect any part of the esophagus, but is usually located in the upper or middle third. "The results showed that among 10 ESCC patients, mRNA expression of CD22 in esophageal squamous cell carcinoma was higher than in para-cancerous tissue in 5 patients." (PMID 37817249, 2023). "KYSE140 and KYSE150 cells expressed CD22 mRNA, and in ESCC patients, mRNA expression of CD22 in esophageal squamous cell carcinoma was higher than in para-cancerous tissue." (PMID 37817249, 2023).
experimental autoimmune encephalomyelitis (1 paper, 2024). An autoimmune demyelinating disease of the central nervous system that is produced experimentally in animals by the injection of homogenized brain or spinal cord in Freund's adjuvant. "Experimental autoimmune encephalomyelitis (EAE) mice were randomized into CD22 blockade and control groups." (PMID 38739106, 2024).
hereditary angioedema (1 paper, 2024). Hereditary angioedema (HAE) is a genetic disease characterized by the occurrence of transitory and recurrent subcutaneous and/or submucosal edemas resulting in swelling and/or abdominal pain. "Other group A proteins mapped to pathways of defective factor XII and defective SERPING1, which cause hereditary angioedema, CD22 (receptor predominantly restricted to B cells)-mediated BCR (B-cell receptors) regulation, and the recycling of bile acids and salts." (PMID 39057787, 2024).
Hydroureter (1 paper, 2025). The distention of the ureter with urine. "On the basis of recurrent hydroureter and progressive disease, he was referred to National Institutes of Health for enrollment to the CD22 CAR-T cell trial." (PMID 40669017, 2025).
intracerebral haemorrhage (1 paper, 2024). "ACT001 attenuates microglia-mediated neuroinflammation after traumatic brain injury, and CD22 blockade modulates microglial activity to suppress neuroinflammation following intracerebral haemorrhage." (PMID 39198723, 2024).
kidney stones (1 paper, 2022). "In the development of kidney stones, CD22 may be involved in recruiting leukocytes and triggering the inflammatory response." (PMID 34997271, 2022).
lentivirus infection (1 paper, 2022). Virus diseases caused by the Lentivirus genus. "T cells were loaded with CD22 CAR via lentivirus infection with an infection efficiency greater than 70% and a copies number of CD22 CAR up to 105/μg genomic DNA." (PMID 35317863, 2022).
lung squamous cell carcinoma (1 paper, 2021). "In the present study, data based on TCGA database, we showed that CD22 was downregulated in LUAD tissue relative to normal tissue, with the same phenomenon reported in lung squamous cell carcinoma." (PMID 33796453, 2021).
lupus erythematosus (1 paper, 2025). An autoimmune, connective tissue chronic inflammatory disorder affecting the skin, joints, kidneys, lungs, heart, and the peripheral blood cells. "Epratuzumab(treatment of lupus erythematosus) induces internalization of CD22 to further disrupt BCR signaling and trigger cell death." (PMID 40988381, 2025).
lymphoproliferative disorders (1 paper, 2019). "We employed both immortalized and primary cells derived from CD22-positive lymphoproliferative disorders to investigate the signaling pathways contributing to IO sensitivity or resistance." (PMID 30834235, 2019).
macrophage activation syndrome (1 paper, 2020). A complication of rheumatic disease that is caused by excessive activation and uncontrolled proliferation of T lymphocytes and well-differentiated macrophages. "The primary CD19/CD22 CAR T cell-attributable toxicity observed was one instance of grade 1 and 2 CRS, which was similar to macrophage activation syndrome." (PMID 32245502, 2020).
malaria (1 paper, 2019). Malaria is a serious and sometimes fatal disease caused by a parasite that commonly infects a certain type of mosquito which feeds on humans. "Earlier work also showed that in addition to FcRL5 (a potential inhibitory receptor) the expression of two inhibitory receptors, CD85j and CD22, were upregulated in malaria-associated atypical MBCs as compared to classical MBCs." (PMID 31068937, 2019).
medulloblastoma (1 paper, 2021). A malignant, invasive embryonal neoplasm arising from the cerebellum. "To test the ability of CD19/20/22CAR T-cells to distinctly target CD19, CD20, and CD22, we force-expressed these molecules individually on Daoy medulloblastoma cells, which are null for all three antigens." (PMID 32205861, 2021).
metastasis (1 paper, 2023). The spread or migration of cancer cells from one part of the body (where they first appeared) to another. "Based on the relationship between CD22 expression and clinical parameters, CD22 in esophageal squamous cells may contribute to lymph node metastasis." (PMID 37817249, 2023).
mucositis (1 paper, 2017). Mucositis is inflammation and damage of the mucous membranes lining the mouth and other parts of the gastrointestinal (GI) tract. "The levels of CD22 and CD200 expression were independent of the mucositis grade." (PMID 28052121, 2017).
myelitis (1 paper, 2024). An inflammatory process affecting the spinal cord. "Since myelitis is a characteristic pathological change in EAE mice, increased expression of microglial CD22 in the spinal cord may be associated with increased severity of inflammatory stimuli." (PMID 38739106, 2024).
Niemann-Pick disease (1 paper, 2020). A group of inherited, severe metabolic disorders in which sphingomyelin accumulates in lysosomes in cells. "For example, CD22 responds to 2-hydroxypropyl-beta-cyclodextrin, which is in phase 2 and 3 clinical trials for Niemann–Pick disease, to reduce microglia-associated defects, and antibodies directed against CD22 reduce microglial impairment in aging brains." (PMID 32317254, 2020).
Obesity (1 paper, 2025). Accumulation of substantial excess body fat. "Sex-differential disease-related genes include those associated with obesity (PPARG, INSR), cancer (FGFR1, CD22), and immunity (IL6R, IL3RA)." (PMID 40707586, 2025).
pancreatitis (1 paper, 2026). Inflammation of the pancreas. "The CellChat-inferred ligand–receptor pairs highlight putative communication axes (e.g., HLA–CD8B, CD22–PTPRC, and ANXA1–FPR1) that could mediate pathogenic inflammation or immune regulation in pancreatitis." (PMID 41601670, 2026).
Pleural effusion (1 paper, 2020). The presence of an excessive amount of fluid in the pleural cavity. "The FL‐SJC cells expressed CD19, CD10, CD22, HLA‐DR, CD38, Lambda and CD20, but did not express CD23, CD5 and Kappa, which was similar to that of the original FL cell from pleural effusion." (PMID 32459397, 2020).
pneumococcal infection (1 paper, 2020). Infections with bacteria of the species streptococcus pneumoniae. "The study shows to a new role for CD22 and indicates a new potential target for treatment of pneumococcal infections." (PMID 32324805, 2020). "In this study we identified a gene, the Cd22 gene, that controls resistance to pneumococcal infection." (PMID 32324805, 2020). "After pneumococcal infection, very different survival rates were observed between C57BL/6 (CD22-positive) and mice with a CD22-deficiency on a C57BL/6 background." (PMID 32324805, 2020).
retinoblastoma (1 paper, 2025). A malignant tumor that originates in the nuclear layer of the retina. "KEGG analysis revealed five pathways positively associated with DBF4B expression: retinoblastoma gene cancer, resolution of sister chromatid, CD22-mediated BCR regulation, kinesins, and the role of phospholipids in phagocytosis." (PMID 40535802, 2025).
Splenomegaly (1 paper, 2018). Abnormal increased size of the spleen. "Both aged Cav1+/− and Cav1−/− mice present with decreased CD19+CD22+ B cells and secondary-follicle atrophy, specifically in the spleen, compared with wild-type controls and irrespective of splenomegaly status." (PMID 30005686, 2018).
staphylococcal infection (1 paper, 2020). An infection caused by Staphylococcus. "Hence, a single publication reported CD22–/–mice have normal morbidity and mortality after staphylococcal infection." (PMID 32324805, 2020).
systemic inflammatory response syndrome (1 paper, 2021). SIRS is a serious condition related to systemic inflammation, organ dysfunction, and organ failure. "Currently, various groups are working on addressing different targets such as CD22 for patients with CD19 negative relapses, optimizing the dose of CAR-T cells, and standardizing the management of neurological toxicity and systemic inflammatory response syndrome (SIRS)." (PMID 33540543, 2021).
T-cell leukemia (1 paper, 2018). A malignant disease of the T-lymphocytes in the bone marrow, thymus, and/or blood. "For verification of specificity of dDT2219 (DT2219 and BIC as controls), we performed a proliferation assay with HPB-MLT cells (T-cell leukemia cell line expressing CD3 but not CD19 or CD22)." (PMID 29316610, 2018).
thalassemia (1 paper, 2020). An inherited blood disorder characterized by a decreased synthesis of one of the polypeptide chains that form hemoglobin. "Overall, we identified 83 carriers of four separate β‐thalassemia pathogenic variants: three β0‐thalassemia [CD22 (GAA→TAA), initiation codon (ATG→ACG), and IVS1‐3ʹ end del 25bp] and one β+‐thalassemia pathogenic variants (IVS‐I‐110 (G→A))." (PMID 32394645, 2020).
tumor (193 papers, 2005 to 2026). "All results demonstrate that PD‐L1 induction on the CD22 CAR‐T cells is specifically associated with tumor cell stimulation." (PMID 35665369, 2022). "These assays usually showed relatively low levels of Moxe during the first dose, due to the high CD22 density on tumor cells causing a CD22-sink." (PMID 32756468, 2020). "Drawing on results obtained from different tumor models, it appears that the membrane micro domains specifically harboring the CD22 molecule are susceptible to the actions of cytokines, especially IL-4." (PMID 32012891, 2020). "FACS analysis of bone marrow from the three patients with disease relapse following bispecific CD19/CD22 CAR T cell therapy indicated two major patterns: relapse of antigen-positive tumor cells and relapse associated with antigen loss." (PMID 32245502, 2020). "CAR T cells are deficient in recognizing tumor cells expressing low levels of target antigen, providing an opportunity for immune escape through antigen downregulation, as has been observed in clinical trials of CD22 and BCMA CARs10–12." (PMID 41131392, 2025). "Thus, the creation of autologous CAR-T cells targeting two antigenic profiles, CD19 and CD22, represents an innovative approach to counteract the acquisition of tumour cell resistance to CAR-T through loss of the mono-antigenic target." (PMID 38444031, 2024). "Furthermore, the positive association between CD22 and the size of the tumor (one of the crucial clinical pathological parameters with considerable prognostic and predictive value) suggests that CD22 can be used as a prognostic biomarker in TNBC." (PMID 36768478, 2023). "Similarly, tumor escape via CD22 antigen loss has been observed in up to 30% of patients with B-ALL treated with CD22-specific CAR T cells." (PMID 34771652, 2021). "However, unlike CD19, the development of resistance to CD22-directed therapies has been associated with the selection of tumor subclones with low (but detectable) CD22 protein expression rather than the acquisition of CD22 coding mutations or modulation of CD22 mRNA expression or splicing." (PMID 34113750, 2020). "In the last few years, several anti-CD20 and anti-CD22 ITs composed of mAbs linked to RIPs, bacterial toxins, ribonucleases, drugs, or radioisotopes have demonstrated potent anti-tumor effects in vitro and in vivo in animal models and, in some cases, also in clinical trials." (PMID 28556822, 2017). "The biopsy results revealed the presence of CD19+CD22+ cells in Patient 3 at the time of relapse, indicating significant resistance of the tumor cells and a highly suppressive tumor microenvironment." (PMID 41550973, 2026). "Its enhanced CD22 targeting capability effectively leverages a dual-targeting approach to address antigen escape and tumor heterogeneity." (PMID 41550973, 2026). "Recently, various CAR constructs for CD19 and CD22 dual targeting have been designed, effectively overcoming tumor heterogeneity and reducing the recurrence rates." (PMID 41550973, 2026). "CD19/CD22 dual-target CAR T is more likely to target tumor cells with high CD22 expression, reduce overkill of normal B-cells, and thus reduce the total amount of systemic inflammatory factors (such as IL-6, IFN-γ) released." (PMID 40433368, 2025). "Immunostaining revealed CD19 expression in 15% of tumor cells and CD22 expression in nearly all cells (95%)." (PMID 41235228, 2025). "Fusion with monoclonal antibodies (e.g., antibodies against tumor-associated antigens, such as HER2 and CD22) or other targeting ligands (e.g., IL-2) creates ITs capable of specifically targeting specific tumor cells." (PMID 40303490, 2025). "Affinity-tuned dual-targeting CARs also widen therapeutic windows; lower-affinity CD22-CARs paired with CD19-CARs selectively eliminate high-antigen-expressing tumor cells, sparing normal tissues." (PMID 41348261, 2025).